TMEM106B (transmembrane protein 106B)
Diseases named in the same sentence as TMEM106B in open-access papers (continued):
Sharing a sentence is not in itself a finding about the gene and the disease.
tumor (6 papers, 2018 to 2025). "Overall, 16% of the tested tumours (4/25) harboured oncogenic fusion genes and we identified TMEM106B::ROS1 as a new fusion gene for CCA." (PMID 38877653, 2024). "It functions as a molecular sponge for miR-3163, inhibiting the suppressive effect of miR-3163 on TMEM106B, which results in the upregulation of TMEM106B expression and consequently fuels tumor cell proliferation and migration." (PMID 39336798, 2024). "The results indicate that TMEM106B induces the production of enlarged lysosomal vesicles laden with bioactive cathepsins, which undergo Ca2+-dependent lysosomal exocytosis that enhances the invasion and migration of the tumor cells." (PMID 30013069, 2018). "We observed that in each of the different human and murine tumor cell models, upon TMEM106B induction, the enlarged lysosomes are loaded with active cathepsin B as evident from the enhanced red fluorescence in the lysosomal vesicles and significant increase in florescence intensity." (PMID 30013069, 2018). "We identified FGFR2::BICC1 fusions in two tumours, and FGFR2::KCTD1 and TMEM106B::ROS1 as novel fusions with potential therapeutic implications in iCCA and confirmed oncogenic properties of TMEM106B::ROS1 in vitro." (PMID 38877653, 2024). "However, recent studies showed that different BRAF fusions, such as GTF2I-BRAF, DGKI-BRAF, and TMEM106B-BRAF, activated the MAPK pathway, thereby regulating tumor growth in multiple cancers." (PMID 30111351, 2018). "Though primary tumor sizes for all the candidate lines were not significantly different from each other or control, TMEM106B overexpressing cells showed significantly higher numbers of in vivo metastasis compared to Mcherry control cells." (PMID 30013069, 2018).
cancer (5 papers, 2018 to 2026). A tumor composed of atypical neoplastic, often pleomorphic cells that invade other tissues. "We acknowledge the fact that cancer cells with elevated TMEM106B expression produce very large amounts of intracellular active cathepsins." (PMID 30013069, 2018). "While the protein has not been thoroughly studied in the context of cancer, TMEM106B loss-of-function is known to be associated with frontotemporal lobar degeneration, and is also repressed in the brains of Alzheimer’s patients." (PMID 30013069, 2018). "We also demonstrate that TMEM106B-induced lysosomes undergo calcium-dependent exocytosis, thereby releasing active lysosomal cathepsins necessary for TMEM106B-mediated cancer cell invasion and metastasis in vivo, which could be therapeutically prevented by pharmacological inhibition of cathepsins." (PMID 30013069, 2018).
neurological disease (5 papers, 2021 to 2025). "Mutations in lysosome gene products including the TMEM106B protein are associated with many types of glial and neurological diseases." (PMID 39194695, 2024). "Whether alteration of GalCer and/or sulfatide levels is responsible for TMEM106B-associated neurological diseases such as HLD requires further investigation." (PMID 40713630, 2025). "In recent years, TMEM106B has been linked to many neurological disorders and genome wide association studies has recently found that TMEM106B may play a role in PD, demonstrating a vital role for endolysosomal processing in PD." (PMID 36704248, 2022). "In summary, rs1990622 variant showed different association with TMEM106B expression in neuropathologically normal individuals and neurological disease individuals (Mayo and ROSMAP)." (PMID 33461566, 2021). "We will discuss the T185S variant below in the sections “Endolysosomal functions of TMEM106B” and “Mouse models of PGRN- and/or TMEM106B-associated neurological diseases”." (PMID 40713630, 2025). "Hence, the most significant association between rs1990622 T allele and reduced TMEM106B expression identified in neuropathologically normal individuals was not successfully replicated in neurological disease individuals." (PMID 33461566, 2021).
psychiatric disorder (1 paper, 2025). A disorder characterized by behavioral and/or psychological abnormalities, often accompanied by physical symptoms. "Twelve lead SNPs were located within 10 genes (BIN1, TMEM106B, AP001257.1, PICALM, SLC24A4, PVRL2, APOE, CLPTM1, CTB-179K24.3, and CASS4) for AD, and all three stress-related psychiatric disorders were identified using FUMA." (PMID 39975850, 2025).
TMEM106B also shares sentences with these, for which no sentence is quoted: progressive supranuclear palsy (3 papers); Stroke (3); coronary artery disease (2); multiple system atrophy (2); angina pectoris (1); arteriolosclerosis (1); astrocytomas (1); atrial fibrillation (1); bipolar disorder (1); breast carcinoma (1); cerebrotendinous xanthomatosis (1); Delusion (1); demyelination (1); diabetes (1); Down syndrome (1); Dyskinesia (1); frontotemporal lobe dementia (1); Gaucher disease (1); genetic disorders (1); glioblastoma (1); GM2 gangliosidosis (1); Hypertension (1); ischemic stroke (1); Lewy body disease (1); metachromatic leukodystrophy (1); mood disorder (1); multiple sclerosis (1); Nasu-Hakola disease (1); neuronal ceroid lipofuscinosis (1); Nystagmus (1).
A further 5 diseases each share a sentence with TMEM106B in 1 paper.